FTO (FTO alpha-ketoglutarate dependent dioxygenase)
Diseases named in the same sentence as FTO in open-access papers (continued):
Sharing a sentence is not in itself a finding about the gene and the disease.
cancer (continued). "It is worth noting that the development of clinically applicable selective and effective inhibitors of FTO and other m6A regulatory proteins may provide new and more effective treatment strategies to treat cancer, especially when used in combination with emerging immunotherapies." (PMID 32443966, 2020). "FTO affected the expression of miR-130, miR-155 and miR-378 involved in brown adipogenesis, suggesting the existence of the cross-regulation network between FTO and miRNAs and the possibility that FTO might target miRNAs to regulate the phenotypes of cancer cells." (PMID 32209098, 2020). "Recent studies showed that the level of FTO gene expression in cancer cells is dramatically increased and may play a role in the growth of these cells through the regulation of the cellular metabolic pathways, including the phosphoinositide 3-kinases/protein kinaseB (PI3K/AKT) signaling pathway." (PMID 31447604, 2019). "Furthermore, Kaplan-Meier, meta-analysis and univariate Cox assay showed that the expression of m6A members including METTL3, METTL14, WTAP and FTO but not their gene mutation and amplification, was tightly associated with cancer progression and poor survival." (PMID 30953473, 2019). "For example, FTO-mediated m6A modification of lncRNA LINC00022 improves its stability and stimulates cancer cell proliferation by recognizing YTHDF2." (PMID 39904996, 2025). "m6A regulators include writers (METTL3, METTL14, KIAA1429, and ZC3H13), erasers (ALKBH5 and FTO) and readers (YTHDF1/2/3, IGF2BP1/2/3), which are thought to play important roles in regulating cancer progression." (PMID 40774945, 2025). "Collectively, these studies indicate that pharmacological inhibition or silencing of FTO and ALKBH5, two critical demethylases, can substantially sensitize cancers to ICI therapy." (PMID 39987091, 2025). "In cancer, aberrant expression of m6A-modifying enzymes such as METTL3 and FTO drives malignant phenotypes, including cell proliferation, metastasis, metabolic reprogramming, and immune evasion." (PMID 41446042, 2025). "FTO can inhibit the expression of apolipoprotein E (APOE) and repress the glycolysis and cancer growth in an m6 A-dependent manner." (PMID 40483535, 2025). "The treatment of pNENs cells with increasing concentrations(μM) of the FTO inhibitor FB23 resulted in a dose-dependent increase in cell mortality, indicating its anti-cancer effects." (PMID 39990672, 2025). "Another small-molecule inhibitor of FTO, CS1/CS2, suppresses cancer stem cell maintenance and immune evasion by targeting FTO activity on MYC and CEBPA mRNAs." (PMID 41373022, 2025). "On the one hand, the overexpression of FTO has been identified as an oncogene that triggers the demethylation of PKM2, changing the metabolism of cancer cells towards aerobic glycolysis." (PMID 41157107, 2025). "Recent studies have highlighted the various roles of FTO and ALKBH5 in tumorigenesis and cancer progression." (PMID 40361322, 2025). "Targeting the m6A machinery-including FTO, a demethylase-or METTL3-has become a possible approach for cancer treatment." (PMID 40530256, 2025). "FTO has been shown to play an important role in HCC progression through the promotion of hepatic inflammation and cancer stemness." (PMID 38256056, 2024). "Previous studies have demonstrated the critical role of M6A regulators FTO, IGF2BP2 and IGF2BP3 in ovarian and other cancers." (PMID 38714753, 2024). "We collected PB from healthy controls (HCs) and patients with CRC, analyzed PB RNA m6A levels and the expression of m6A-related demethylase genes FTO and ALKBH5, cocultured CRC cells with PB mononuclear cells (PBMCs), and constructed an MC38 cancer model." (PMID 38439072, 2024). "In summary, the abnormal expression of FTO and ALKBH5 affects the expression level of m6A, which further affects the development of cancer, indicating that they have the potential to be prognostic biomarkers for various cancers." (PMID 38166832, 2024).
cancer (continued). "Future preclinical studies, i.e., using inhibitors of both FTO and ALKBH5, are thus needed to evaluate the role of the ALKBH5 FTO-ATF4 axis in the resistance of cancer cells to treatment." (PMID 39199320, 2024). "A total of 5856 DEGs were obtained in between NC and FTO depleted AGS cell groups, and involved in the cancer related pathways." (PMID 38200441, 2024). "Changes in FTO and METTL14 levels largely affect the in vitro proliferation, migration, and invasion of cancer cells." (PMID 38491196, 2024). "Understanding the distinct mechanisms of action of FTO and ALKBH5 in tumors is crucial for unraveling the molecular underpinnings of cancer development and providing insights for developing targeted therapeutic strategies." (PMID 39192357, 2024). "CESC, BRCA, LUAD, and COAD cell lines express lower amounts of METTL3 and FTO transcripts compared to their healthy counterparts, while WTAP and ALKBH5 expressions differ by cancer type." (PMID 38665783, 2024). "In lung adenocarcinoma, Wnt/β‐catenin signaling, along with YTHDF1, inhibits FTO expression and subsequently enhances c‐MYC expression, thereby promoting aerobic glycolysis and malignant behavior in cancer cells." (PMID 38721006, 2024). "In addition to ALKBH5, FTO could also affect cancer biology by targeting lncRNAs." (PMID 38075202, 2024). "However, the definitive role of FTO in cancer remains unclear." (PMID 38491196, 2024). "Later, they discovered that FTO inhibitors CS1 and CS2 can inhibit the self-renewal of cancer stem cells and enhance T cell toxicity." (PMID 39280246, 2024). "Among m6A regulators, METTL3/14, FTO, ALKBH5, and members of the YTHDF family have been extensively studied for their contributions to RNA regulation and cancer progression." (PMID 39247830, 2024). "Several improved FTO inhibitors have also been developed since 2020, such as CS1/CS275 and Dac51,76 which suppress cancer cell proliferation and cancer stem cell self-renewal as well as enhance anti-tumor immunity." (PMID 39524541, 2023). "Only after recognizing FTO and ALKBH5 as mRNA demethylases have their epigenetic regulatory roles in cancers been gradually emphasized." (PMID 37007161, 2023). "Further, multiple inhibitors targeting FTO such as meclofenamic acid (MA), R-2-Hydroxyglutarate (R-2HG), FB23, and FB23-2, exert anti-cancer effects by selectively inhibiting the activity of FTO." (PMID 37443100, 2023). "Since it was confirmed that FTO can promote NSCLC cell migration and invasion, the potential mechanism by which FTO facilitates cancer metastasis in NSCLC needed to be further investigated." (PMID 37919739, 2023). "We summarize the mechanisms of m6A involvement in cancer and list potential cancer therapy inhibitors that target m6A regulators such as “writer” METTL3 and “eraser” FTO." (PMID 39872957, 2023). "Subsequently, they developed two other FTO inhibitors, CS1 and CS2, which exhibited strong antitumor effects in various cancers." (PMID 38117350, 2023). "This suggests that FTO and ALKBH5 demethylases can act as therapeutic targets and their inhibitors as potential m6A-targeting anti-cancer drugs." (PMID 37958565, 2023). "Suppression of ferroptosis, a novel iron-dependent form of cell death, was shown to be essential for cancer malignant behavior, and m6A regulators such as METTL14, FTO, YTHDF2 and YTHDC2 are involved in regulating ferroptosis." (PMID 37015927, 2023). "Down‐regulated FTO in LC cells promoted the translation of MYC mRNA and increased glycolysis and cancer progression." (PMID 36260366, 2023). "Some small activators as well as inhibitors of METTL3, FTO, and YTHDF1–3 were designed to treat different cancers both in vitro and in mouse models." (PMID 36795489, 2023). "The same study also found that FTO promoted cancer development and proliferation of arecoline‐transformed OSCC by maintaining cancer stemness and mediating cisplatin resistance." (PMID 35560957, 2023).
cancer (continued). "An increasing number of studies have confirmed that m6A writers (METTL3, METTL14, KIAA1429, WTAP), erasers (FTO and ALKBH5) and readers (YTHDC1, YTHDC2, YTHDF1, YTHDF2 and HNRNPC) have distinct functions within different types of cancer cells." (PMID 35042525, 2022). "Conversely, FTO represses the glycolysis of PTC by destabilizing APOE, thus restraining the growth of cancer." (PMID 35804965, 2022). "In cervical squamous cell carcinoma, FTO reduces β-catenin transcript, and promotes ERCC1 activity, thus enhancing chemo-radiotherapy resistance of cancer cells." (PMID 35022030, 2022). "Most m6A methyltransferases and demethylases have been intensively investigated in cancers, such as METTL3, METTL14, FTO, and ALKBH5." (PMID 35596159, 2022). "The involvements of METTL3, METTL14, FTO, and ALKBH5 in many cancers have been investigated, and they demonstrate various roles in different cancers." (PMID 35596159, 2022). "The keywords used included: “m6A demethylases”; “FTO”; “AKBH5”; “inhibitors”; “crystal structure”; “human diseases”; “cancer”; and “therapy responses”." (PMID 35628623, 2022). "Here, we found that PIKE-A promoted SDHA expression via increasing FTO expression through activation of STAT3 signaling and maintaining mitochondrial membrane potential, leading to promoting cancer cell proliferation." (PMID 36232604, 2022). "Studies have found that R-2HG can inhibit activity of the m6A eraser FTO, increase m6A modification, and reduce the stability of the MYC/CEBPA transcript to exert an anti-cancer effect." (PMID 36360248, 2022). "For instance, m6A demethylases, such as FTO and ALKBH5, was shown to be essential for glioblastoma cancer stem cells and they mediate resistance to conventional chemotherapy and cancer recurrence in, respectively." (PMID 35884552, 2022). "m6A can be dynamically removed by “erasers” such as FTO (FTO alpha-ketoglutarate-dependent dioxygenase) or ALKBH5 (AlkB homolog 5, RNA demethylase) in response to environmental stimuli including memory formation, cancer development and stress responses." (PMID 36250017, 2022). "The FB23-2 compound not only showed specific inhibition against FTO and proliferation against the AML cancer cell line in vitro, but also inhibited the progression of leukemia and prolonged the survival time in an in vivo AML model." (PMID 36360248, 2022). "As m6A demethylase, FTO and ALKBH5 were reported to play critical roles in multiple cancers and are involved in cancer drug resistance." (PMID 34745970, 2021). "Subsequently, m6A RNA methylation erasers, FTO and ALKBH5, were identified to be dysregulated in HNSCC and other cancers." (PMID 34207099, 2021). "In breast cancer, FTO has been shown to enhance the PI3K/AKT signaling pathway and degrade BNIP3 (a mitochondrial pro-apoptotic protein) mRNA transcripts, promoting cancer cell growth." (PMID 33922187, 2021). "We first elucidated the expression characteristics of these regulators in a pan-cancer context: (i) Expression changes of some clusters (YTHDF family, IGF2BP family, METTL14, FTO, and ALKBH5) were consistent in selected cancers." (PMID 33718187, 2021). "Inhibition of m6A (METTL14 knockout) promotes the proliferation and invasion of cancer cells by activating the Wnt and PI3K Akt signals, while elevation of m6A (FTO knockout) reverses these phenotypes." (PMID 34489709, 2021). "In other types of cancer, ALKBH5 and FTO also participate in many pathological and biological activities, referring to proliferation, apoptosis, migration, invasion and metastasis." (PMID 34895230, 2021). "Consistent with this, in a subsequent study of the same group, targeting FTO induced a similar effect on FTO/m6A/MYC/CEBPA axis signaling through the same mechanism, leading to cell-cycle arrest in cancer stem cells." (PMID 33842477, 2021). "FTO and ALKBH5 inhibit proliferation by regulating cell migration, invasion, and metastasis in some cancer cells." (PMID 34630412, 2021).
cancer (continued). "Several recent studies highlighted the vital roles of FTO and ALKBH5 in cancer progression by regulating the stability and functions of some key ncRNAs." (PMID 32209098, 2020). "Among these cancer relapse-relevant genes, METTL16, FTO, EIF3D, and EIF3I were good prognostic factors, while TRA2A, HNRNPA2B1, and YTHDC2 were bad ones." (PMID 33273988, 2020). "Implications of METTL3, METTL14, FTO, ALKBH5, and YTHDF2 have been demonstrated in several types of cancer such as acute myeloid leukemia, hepatocellular cancer, and glioblastoma." (PMID 33273988, 2020). "Apart from FTO, ALKBH5 is another m6A eraser that has been shown to be pivotal for tumorigenesis and cancer stem cell self-renewal in AML." (PMID 32916783, 2020). "Although both FTO and ALKBH5 belong to the AlkB family, they have differing substrate specificity for human cancers." (PMID 32296573, 2020). "The two key demethylases, FTO and ALKBH5, were also involved into the regulation of cancer progression as mRNA handlers." (PMID 32209098, 2020). "Earlier studies have revealed the critical role of m6A regulators, particularly METTL3, METTL14, FTO and ALKBH5 in driving cancer progression and metastasis." (PMID 31069256, 2019). "Moreover, FTO promotes the expression of SLC7A11 and GPX4, thereby reducing cancer cell ferroptosis in animal models and in vitro." (PMID 40823087, 2025). "In recent years, many inhibitors that target RNA modifications, such as small-molecule inhibitors of FTO and ALKBH5, which inhibit immune escape from tumors by targeting m6A modifications to inhibit the growth of many cancers, have been developed and investigated in clinical studies." (PMID 40360483, 2025). "Among young women, FTO levels were significantly elevated in comparison to those of women without cancer." (PMID 39820532, 2025). "Tissue factor pathway inhibitor 2 (TFPI‐2) mRNA is m6A‐modified and stabilized by binding to YTHDF1, which upregulates TFPI‐2 expression and suppresses tumor growth, migration, and invasion, but removal of m6A‐modification by FTO reduces TFPI‐2 expression and promotes cancer progression." (PMID 40448344, 2025). "Using both depletion approaches, only 4 out of 1183 cancer cell lines exhibited dependence on FTO in the CRISPR screen, and no cell lines were dependent in the RNAi screen." (PMID 41279954, 2025). "Additionally, FTO and ALKBH5 play a significant role in the progression of various kinds of cancer, mainly by controlling the stability of miRNAs and increasing their expression in a m6A-depended way." (PMID 39904996, 2025). "We found that not many studies have been reported on FTO rs1121980, especially its impact on cancer." (PMID 40391584, 2025). "Furthermore, FTO can stabilize mRNA transcripts of MYC and CCAAT enhancer binding protein alpha (CEBPA), increasing the proliferation and survival of cancer cells." (PMID 40483535, 2025). "We further show that FTO‐mediated m6A‐dependent regulation of IGFBP3 expression leads to activation of the AKT signalling pathway and modulates key malignant behaviours involved in cancer progression." (PMID 40621649, 2025). "Furthermore, FTO inhibitors can regulate the Wnt/PI3K–AKT signaling pathway, affecting cancer metastasis." (PMID 39802639, 2025). "Nevertheless, current studies have not shown a connection between FTO SNPs and FTO expression in cancer patients." (PMID 40722726, 2025). "FTO mRNA was significantly upregulated in 11 cancer types, downregulated in 4 cancer types, and showed no significant change in the remaining 4 types." (PMID 40621649, 2025). "The m6A erasers FTO and ALKBH5 also mediate chemoresistance in cancer." (PMID 38545841, 2024). "Notably, FTO, ALKB homologue, and TET inhibitors have demonstrated efficacy in suppressing cancer cell proliferation and enhancing therapeutic outcomes." (PMID 38943267, 2024).
cancer (continued). "Although small molecules such as compound 21 (Rhein), compound 22 (Clausine E), compound 23 (Diacerein) and compound 29 (CHTB) exhibit FTO inhibitory activity, their therapeutic effects on specific cancers have not been reported." (PMID 38711100, 2024). "Studies have confirmed that low expression of FTO in a hypoxic environment accelerates the malignant progression of colorectal cancer (CRC), while high expression of ALKBH5 significantly promotes female malignant tumors." (PMID 39033180, 2024). "Our previous studies showed that FTO protects CRC cells from ferroptotic cell death, thus, we wonder whether pharmacological blocking of FTO would as a potential therapeutic approach in cancer with a ferroptotic cell death." (PMID 38600610, 2024). "A large number of studies of m6A regulatory mechanisms have investigated classical m6A regulators, such as METTL3, METTL14, WTAP, METTL16, FTO, ALKBH5, YTH family proteins, and IGF2BPs; anti-cancer target drugs targeting METTL3 and FTO have been proven to be effective against cancer." (PMID 38970366, 2024). "Moreover, the mRNA expression of FTO and ALKBH5 in the PB of MC38 cancer model mice was also decreased compared with those in the PB of the control mice (P < 0.05)." (PMID 38439072, 2024). "Unlike previous studies, which reported that FTO is highly expressed in various cancers, levels of FTO were reported to be downregulated in clinical ICC samples and cell lines." (PMID 39691597, 2024). "Previous studies have shown that FTO and ALKBH5 play a cancer-suppressive role in CRC." (PMID 37580808, 2023). "The m6A-dependent modification is reversible and regulated by methyltransferases (METTL3, METTL14, and WTAP), demethylases (FTO and ALKBH5), and m6A-binding proteins (such as YTH domain family proteins and IGF2BP family proteins), which are essential for cancer initiation and progression." (PMID 37580808, 2023). "Similarly, four representative CRC tissues showed lower FTO and ALKBH5 expression levels than the corresponding para-cancer tissues." (PMID 37580808, 2023). "Therefore, understanding the role of FTO in CRC is very important, especially to find out the effective target for treatment to fight against cancer." (PMID 36874096, 2023). "FTO inhibitors such as Meclofenamic acid (MA), FB23-2, and R2 hydroxyglutarate (R2HG) have been recently investigated as anticancer drugs in many types of cancer." (PMID 37543622, 2023). "In conclusion, akin to METTL3, METTL4, METTL16, WTAP, RBM15/15B, VIRMA, and ZC3H13, the potential influence of YTHDC1, YTHDC2, YTHDF, IGF2BPs, the HNRNP family, eIF3, FTO, and ALKBH3/5 on autophagy is intertwined with their roles in RNA metabolism, collectively regulating autophagy in cancer." (PMID 38148841, 2023). "In contrast, ZC3H13, IGF2BP1, WTAP, FTO, and YTHDC2 were downregulated in ≥four cancer types." (PMID 35211628, 2022). "Inhibition of FTO with shRNAs was sufficient to suppress the expression of ZEB1 and Vimentin, promote E-cadherin expression levels, and attenuate docetaxel resistance of cancer cells following SN-exo incubation." (PMID 36302751, 2022). "In addition to FTO, the m6A writer METTL3 has also become a new target for anti-cancer drug development." (PMID 36360248, 2022). "One study found that METTL3 but not FTO is significantly increased in cancer tissues, whereas the other study found that both were significantly increased." (PMID 35155557, 2022). "Moreover, proteins responsible for m6A modification, including writers (such as METTL3/14), erasers (such as FTO and ALKBH5), and readers (such as YTHDF1/2/3), have been found to be overexpressed and promote the initiation and development of many cancer types." (PMID 35986274, 2022). "Two FTO inhibitors, FB23 and FB23-2, can attenuate the activity of FTO demethylase by directly binding to the activity pocket of FTO demethylase, resulting in a significant lethal effect on cancer cells." (PMID 36553648, 2022).